ITCH (itchy E3 ubiquitin protein ligase)
Diseases named in the same sentence as ITCH in open-access papers (continued):
Sharing a sentence is not in itself a finding about the gene and the disease.
tumor (continued). "We found that expression of a nuclear form of ITCH was significantly increased in human TNBC cell lines and tumor specimens." (PMID 30517763, 2019). "Although previous studies hinted the possible involvement of WBP2 in inflammation, via its binding to ITCH, a negative regulator of TNF/NF‐κB signaling, this study shows for the first time a participatory role of WBP2 in tumor inflammatory signaling, particularly in TNF/NF‐κB signaling pathway." (PMID 34197030, 2022). "Circ-ITCH specifically targets miR-106b-5p and miR-421 in clear cell renal cell carcinoma (ccRCC) and oral squamous cell carcinoma (OSCC) to up-regulate PDCD4 expression and prevent tumor progression, respectively." (PMID 35910224, 2022). "However, studies analyzing the expression and function of ITCH in CRC show that ITCH is downregulated in CRC and acts as a tumor suppressor by inhibiting the Wnt/β-catenin pathway." (PMID 33968776, 2021). "However, ITCH has been found to play contrasting roles in mediating Hippo signalling and cancer promotion by degrading LATS1, a known tumour suppressor." (PMID 34831354, 2021). "Furthermore, doxycycline-induced ITCH depletion in WM1346 cells significantly suppressed the p-MEK/p-ERK signaling and tumor growth in vivo." (PMID 31015455, 2019). "We found the level of circ-ITCH expression was positively correlated with histological grade (P = 0.034), but not with other clinicopathological characteristics, including age, tumor node metastasis stage (TNM) and tumor size." (PMID 29386015, 2018). "ITCH-mediated HER3 ubiquitination and degradation by 9F7-F11 could partly explain why this therapeutic antibody reduced tumor xenograft growth in nude mice." (PMID 27203743, 2016). "Two months later, we observed that ITCH expression in MCF10A cells didn't lead to tumor in these mice (data not shown) suggesting that ITCH alone is not enough to transform MCF10A cells." (PMID 25350971, 2014). "Given these contrasting functions of ITCH‐mediated mono‐ and poly‐ubiquitination, targeting ITCH might not be a best option for increasing anti‐tumour immunity but the driving mechanism involved in each case could be considered." (PMID 36881608, 2023). "As a common tumor suppressor in multiple cancers, the function of circ-ITCH in ccRCC is not clear." (PMID 33969128, 2021). "This suggested that other TP73-independent mechanisms may also be involved in ITCH-mediated tumor cell apoptosis, because TP73 is not the sole protein regulated by ITCH." (PMID 31974512, 2020).
cancer (63 papers, 2006 to 2025). A tumor composed of atypical neoplastic, often pleomorphic cells that invade other tissues. "circ-ITCH was a newly identified circRNA; many studies have investigated the association between circ-ITCH expression and prognosis in cancers." (PMID 33623789, 2021). "Despite the relatively low incidence, it highlights the importance of ITCH LOF mutations in cancer biology." (PMID 32393834, 2020). "For example, both circITCH and ITCH were implicated in human cancers by regulating the Wnt signalling pathway." (PMID 30715276, 2019). "Individual cancer susceptibility may be modified by SNPs (rs10485505 and rs4911154) in the circ-ITCH gene region." (PMID 37370928, 2023). "However, further proof-of-concept studies are needed to clarify the exact molecular mechanisms underlying the autophagic activity of ITCH in cancer cells expressing high levels of ITCH." (PMID 36918822, 2023). "Thus, low circ-ITCH expression was significantly associated with aggressive clinicopathological features and unfavorable outcome in various cancers." (PMID 33623789, 2021). "In PCa, evidence suggests that SPOP mediates ITCH ubiquitination and degradation, thereby protecting against cancer metastasis." (PMID 40521202, 2025). "The novel cancer related multifunctional protein MR‐1 (Myofrillogenes regulator‐1) can stabilize the expression of Notch3‐ICD (NICD3) in the cytoplasm through ITCH, which can upregulate many genes related to metastasis to promote the metastasis of NSCLC cells." (PMID 38342606, 2024). "In this article, MR‐1 indirectly exerts its cancer promoting effect by maintaining the stability of NICD3 in the cytoplasm by inhibiting ITCH." (PMID 38342606, 2024). "ITCH inhibition has been shown to augment the effect of chemotherapeutic drugs, suggesting that it is a potential pharmacological target in cancer therapy." (PMID 38597989, 2024). "Existing evidence has highlighted the tumorigenic role of ITCH in different cancers via the blockade of the LATS1-mediated suppression of YAP." (PMID 37568787, 2023). "Circ-ITCH enhanced the expression of its parental gene ITCH by acting as miRNA sponges for miR-7, miR-17, and miR-214, which suppressed the Wnt/catenin signalling pathway and prevented the proliferation of cancer cells." (PMID 37370928, 2023). "Circ-ITCH acts as a miRNA sponge when interacting with miR-216b, miR-7, miR-214, miR-17, and miR-218; it increases the level of ITCH, which is involved in the progress of different cancers via the regulation of the Wnt/beta-catenin pathway." (PMID 37370928, 2023). "Abnormal regulation of circRNA-ITCH can enhance the expression of its parent tumor suppressor gene ITCH by sponging miR-7 and miR-214, thereby regulating the proliferation of cancer cells." (PMID 36474750, 2022). "Circ-ITCH can also function as a miRNA sponge to protect target genes from repression in human cancers of the cervix, breast, ovary, bladder, and papillary thyroid." (PMID 35396504, 2022). "Together, these studies provide new evidence that circ-ITCH is closely related to the regulation of cancer cell metabolism." (PMID 35327551, 2022). "ITCH prevents the development of autoimmune diseases by regulating immune cell biology and controlling cancer progression by targeting p63, p73, Notch1, and Dvl2." (PMID 35327551, 2022). "MiRNAs sponge locations of circ-ITCH downstream in malignant tumors now being researched, including miR-7, miR-10, miR-17, miR-20, miR-22, miR-93, miR-106, miR-145, miR-199, miR-214, miR-216, miR-224, miR-421, miR-524, and miR-615." (PMID 35910224, 2022). "Pooled meta-analysis was performed to estimate the relationship between circ-ITCH expression and clinicopathological features of cancers." (PMID 33623789, 2021). "In this research, we firstly found that circ-ITCH levels were reduced in ccRCC tissues and ccRCC cell lines, which was similar with the fact that it existed the abnormal expression of circ-ITCH in other cancers." (PMID 33969128, 2021).
cancer (continued). "For instance, by acting as a sponge for oncogenic miR-214 and miR-17, circ-ITCH significantly enhances expression of its ITCH linear isoform via competitive interacting with microRNAs, thereby inactivating Wnt/beta-catenin signaling in various cancers." (PMID 33623789, 2021). "Although the correlation between circ-ITCH expression and cancer progression has been investigated by these studies above, most individual studies have been limited by inconsistent conclusions or small sample sizes." (PMID 33623789, 2021). "Circ-ITCH is a well-known circRNA that spans several exons of itchy E3 ubiquitin-protein ligase (ITCH), it exerts inhibitory effects in many cancers through sponging certain miRNAs13,14." (PMID 33795657, 2021). "Based on these limitations above, prospective and well-designed clinical studies with large scale, as well as studies based on other populations beyond China, are still warranted to investigate the role of circ-ITCH in cancer patients." (PMID 33623789, 2021). "Here, we showed that upon incubation of cancer cells with 9F7-F11, the E3 ubiquitin ligase ITCH interacts with c-FLIP to trigger c-FLIP ubiquitination and degradation, concomitantly with early ITCH recruitment to HER3." (PMID 31443721, 2019). "We produced the anti-HER3 antibody 9F7-F11 that promotes HER3 ubiquitination and degradation via JNK1/2-dependent activation of the E3 ubiquitin ligase ITCH, and that induces apoptosis of cancer cells." (PMID 31443721, 2019). "Though dysregulation of circ-ITCH was frequently observed in human cancers, there is currently few consensus concerning the role of circ-ITCH for the cancer prognosis." (PMID 29386015, 2018). "In breast and pancreatic tumors, the expression levels of ITCH correlated with reduced cancer survival." (PMID 29673168, 2018). "Recent studies identified that circ-ITCH Suppresses mutiple cancers proliferation via inhibiting the Wnt/beta-Catenin pathway." (PMID 28636993, 2017). "Recent studies demonstrated that circ-ITCH Suppresses mutiple cancers proliferation via inhibiting the Wnt/beta-Catenin pathway." (PMID 28636993, 2017). "ITCH involved in cancer progression mainly depends on its ability to regulate protein stability and the target proteins including p63, p73, Notch1, Dvl2, RASSF5, and LATS1." (PMID 27642589, 2016). "The E3 ubiquitin (Ub) protein ligase (ITCH) inhibits Wnt/β-catenin signaling in cancers mainly by promoting the ubiquitination and degradation of phosphorylated disheveled 2 (Dvl2)." (PMID 27642589, 2016). "ITCH is a member of the E3 ubiquitin ligases that regulate protein stability and immunological responses, as well as cancer progression." (PMID 25749389, 2015). "Consequently, we compared the expression of ITCH in cell lines from these cancers and focussed our work on the cell line with the highest expression of ITCH, OE33, an oesophageal cell line." (PMID 38216558, 2024). "ITCH is considered to have an important role in cancer development because of its capacity to control the ubiquitination and degradation of several proto-oncogenic proteins such as c-Jun, Cbl-b, and c-FLIP and tumor suppressor proteins, such as p63, p73, and LATS1." (PMID 38597989, 2024). "The data obtained in the present study could also have major implications for understanding how intercellular communication via gap junctions is lost in other cancer types in which ITCH is overexpressed and displays oncogenic features." (PMID 38597989, 2024). "A systematic search in different electronic databases indicated that, among HECT-type E3 ligases, members of the NEDD4 family including NEDD4-1, NEDD4L, SMURF-1, SMURF-2, WWP1, WWP2, and ITCH have been investigated in many various cancers with defective autophagy, as reviewed in next sections." (PMID 36918822, 2023). "miR-106b directly targeted ITCH and inhibited cancer progression." (PMID 37568787, 2023).
cancer (continued). "However, the correlation of circ-ITCH expression with clinicopathological features, as well as the prognosis of cancers, remains inconclusive." (PMID 33623789, 2021). "Thus, we performed this quantitative meta-analysis by systematically evaluating the relationship between circ-ITCH expression and the clinicopathological parameters as well as prognosis of cancers with all eligible articles." (PMID 33623789, 2021). "Recently, circular RNA Itchy E3 ubiquitin protein ligase (circ-ITCH), a novel circular RNA originated from exons of gene itchy E3 ubiquitin protein ligase (ITCH), located on chromosome 20q11.22, was reported to be lower expressed in several cancers." (PMID 33623789, 2021). "Taken together, circ-ITCH could serve as a biomarker for predicting the progression and outcome of cancers." (PMID 33623789, 2021). "Meanwhile, it has been demonstrated that ectopic expression of circ-ITCH was capable of inhibiting cancer growth in vivo, hinting that circ-ITCH might be a potential approach for cancer treatment." (PMID 33623789, 2021). "Studies show that ITCH expression is regulated by microRNAs in cancer." (PMID 33968776, 2021). "The Wnt/β-catenin pathway plays a crucial role during the carcinogenesis of cancers, and we observed that cir-ITCH could negatively regulate Wnt/β-catenin signalling, which could be restored by miR-17." (PMID 33060778, 2020). "Therefore, in future studies it will be paramount to investigate if additional kinases are involved in the activation of ITCH and if ITCH can post-translationally modify various other negative regulators of apoptosis in different cancers." (PMID 31022877, 2019). "Likewise, by sponging the miR-7, miR-17 and miR-214, cir-ITCH can increase the level of ITCH which further inhibits the Wnt pathway that is frequently aberrant in cancers." (PMID 30598076, 2018). "Previous studies indicated that circ-ITCH could promote the expression of its parental cancer-suppressive gene ITCH by sponging miR-7, miR-17, and miR-214." (PMID 30072625, 2018). "Interestingly, ITCH expression was found significantly upregulated in several cancers, such as invasive and metastatic breast cancer, pancreatic tumors, and squamous cancer of the cervix (SCC)." (PMID 29673168, 2018). "As ITCH may modulate several proteins clearly involved in cancer initiation, progression and therapy, it will be intriguing to evaluate whether the ATM-ITCH axis may be relevant in cancer as well." (PMID 25594035, 2014). "Additionally, the miRNA-mediated targeting of ITCH has been shown to promote cancer progression." (PMID 37568787, 2023). "Moreover, the pooled HRs with their 95% CIs showed that low circ-ITCH expression was also significantly correlated with poor OS, implying that low circ-ITCH expression may serve as an indicator of unfavorable prognosis of cancers." (PMID 33623789, 2021). "Therefore, circ-ITCH may serve as a molecular therapy target and a prognostic marker in human cancers." (PMID 33623789, 2021). "Thus, it is worth further exploring the mechanism of circ-ITCH in other cancers." (PMID 32714095, 2020). "To determine whether ITCH-induced c-FLIPL degradation had a major role in anti-HER3 antibody-induced cancer cell apoptosis, we assessed PARP and caspase-8/3 cleavage by western blotting in siITCH and siSC BxPC3 cells incubated with 9F7-F11 alone or with NRG1 for 48 h." (PMID 31443721, 2019). "Also up-regulation of the E3 ubiquitin ligase Itchy (ITCH) could be of potential importance as selective ubiquitin-tagging of signaling proteins for destruction is an emerging mechanism in cancer biology." (PMID 16982006, 2006). "Given that EM shares similar properties with malignant tumors, including the ability of cell migration, the transwell migration assay was further conducted to evaluate the effect of ITGB3/ITCH on the migration of ectopic ESCs." (PMID 37760946, 2023).
cancer (continued). "The ubiquitin E3 ligase ITCH also called atrophin-1 interacting protein 4 (AIP4), has been found to involve in regulating immunological responses and cancer progression." (PMID 36918822, 2023). "Another avenue is to activate ITCH E3 ubiquitin ligase that should lead to downregulation of WBP2 expression and cancer growth." (PMID 32393834, 2020). "For example, TAZ and Nedd4 WW domains interact with the WBP2 PY2 motif, ITCH WW domains 1 and 3 interact with WBP2 PY2 and PY3 motifs to regulate cancer growth, while WWOX and YAP WW domains interact with PY3." (PMID 32393834, 2020). "Previous study has indicated that E3 ligase ITCH can bind and target WBP2 for ubiquitin-dependent proteasomal degradation resulting in the downregulation of WBP2 level and dysfunction in cancer." (PMID 29937544, 2018). "OSMi-mediated inhibition of cancer stem cell phenotypes including mammosphere formation, ALDEFLOUR staining and expression of CSC factors c-Myc and SOX2 were partly reversed in cells containing ITCH knockdown compared to controls." (PMID 40136647, 2025). "Targeting E3 ubiquitin enzymes for cancer therapy has long been considered an attractive mechanism-based drug discovery approach and the possibility of regulating FOXC1 activity via targeting ITCH remains to be seen." (PMID 39171293, 2024). "As circ-ITCH shares some miRNA binding sites with the 3′UTR of ITCH and can regulate linear ITCH expression in different cancers, it is hypothesised that circ-ITCH is a crucial gene in BC development." (PMID 37370928, 2023). "Meta-analysis of the TGCA database revealed that the expression of ITCH does not change significantly in cancer." (PMID 32393834, 2020). "Moreover, inhibition of JNK resulted in the inactivation of ITCH and reduced p-ITCH levels, and consequently c-FLIP levels were restored in cancer cells." (PMID 31022877, 2019). "However, the potential role of ITCH in regulating cancer stem-like cells properties has not been reported." (PMID 40136647, 2025). "AKT activation of ITCH may confer TNBC cells with a DDR repression mechanism to counteract the replication stress constitutively induced by PI3K/AKT signaling, thus increasing cancer cell survivorship and growth potential." (PMID 30517763, 2019). "Besides, there is no consensus about the prognostic value of circ-ITCH expression in cancers." (PMID 33623789, 2021).